RTRAF (RNA transcription, translation and transport factor)
Description:
Accessory subunit of the tRNA-splicing ligase complex that acts by directly joining spliced tRNA halves to mature-sized tRNAs by incorporating the precursor-derived splice junction phosphate into the mature tRNA as a canonical 3',5'-phosphodiester. RNA-binding protein involved in modulation of mRNA transcription by Polymerase II. Could also play a role in RNA transport. (Microbial infection) In case of infection by influenza virus A (IVA), is involved in viral replication.
Synonyms: CLE; hCLE; C14orf166; CGI-99; TSLIG4; RLLM1; CLE7; LCRP369; hCLE1; CGI99
Tractability: PROTAC: ubiquitination databases record sites on it.
Gene: Protein-coding gene on chromosome 14 (51,989,441 to 52,010,694, forward strand). Ensembl gene ENSG00000087302.
Subcellular location: Nucleus; Cytoplasm, cytosol; Cytoplasm, perinuclear region; Cytoplasm, cytoskeleton, microtubule organizing center, centrosome; Cytoplasm
Subcellular location (Human Protein Atlas): Nucleoplasm
Pathways (Reactome):
Metabolism of RNA: tRNA processing in the nucleus
Gene Ontology:
Molecular function: identical protein binding; protein binding; RNA binding; RNA polymerase II complex binding
Biological process: negative regulation of protein kinase activity; positive regulation of transcription by RNA polymerase II; tRNA splicing, via endonucleolytic cleavage and ligation; RNA transport
Cellular component: centrosome; cytoplasm; mitotic spindle; nucleoplasm; nucleus; perinuclear region of cytoplasm; tRNA-splicing ligase complex; cytosol
Genetic constraint (gnomAD): Loss-of-function variants: 7 observed, 20.39 expected, observed/expected ratio (o/e) 0.34, 90% interval 0.19 to 0.64. The upper end of that interval is the gene's LOEUF score, 0.64, which puts it in group 2 of 6, group 1 being the genes least tolerant of losing a copy. Missense variants: 188 observed, 186.71 expected, observed/expected ratio (o/e) 1.01, 90% interval 0.89 to 1.14. Synonymous variants: 66 observed, 62.67 expected, observed/expected ratio (o/e) 1.05, 90% interval 0.86 to 1.29.
Homologues: Orthologues: chimpanzee RTRAF (100% identical), macaque RTRAF (100% identical), pig RTRAF (99% identical), rabbit RTRAF (99% identical), guinea pig RTRAF (98% identical), mouse Rtraf (97% identical), rat Rtraf (97% identical), zebrafish rtraf (84% identical), tropical clawed frog RTRAF (77% identical), Drosophila melanogaster CG31249 (40% identical), Caenorhabditis elegans E02H1.5 (30% identical).
Diseases named in the same sentence as RTRAF in open-access papers:
RTRAF is named in the same sentence as 19 diseases in open-access papers, as found by Europe PMC text mining. Sharing a sentence is not in itself a finding about the gene and the disease.
RTRAF shares sentences with these, for which no sentence is quoted: cancer (3 papers); infection (3); pancreatic cancer (3); tumor (3); lymph node metastasis (2); Alzheimer disease (1); autism (1); bladder cancer (1); brain cancer (1); breast carcinoma (1); cervical cancer (1); deafness dystonia syndrome (1); influenza (1); microcephaly (1); neurodevelopmental disorder (1); non-small cell lung carcinoma (1); pancreatic adenocarcinoma (1); spastic hemiplegia (1); virus infection (1).